LDHA (lactate dehydrogenase A)
Diseases named in the same sentence as LDHA in open-access papers (continued):
Sharing a sentence is not in itself a finding about the gene and the disease.
tumor (continued). "Studies showed LDHA and LDHB both function redundantly in cancer, so targeting both would be more advantageous for therapeutic purposes, In melanoma, cas9-mediated deletion of both isoenzymes showed favorable effects on tumor mass shrinkage." (PMID 37762231, 2023). "Our study revealed that the number of αSMA-positive CAFs was correlated with the expression of LDHA, a master regulator of glycolysis, in PDAC tumors and that PDAC patients with high LDHA mRNA expression had a low number of tumor-infiltrating CD8+ T cells, reflecting an immunosuppressed status." (PMID 37733442, 2023). "Pharmacological inhibition of LDHA with FX11 improved the infiltration and antitumor activity of cytotoxic lymphocytes while reducing the number of CAFs in tumors and suppressing PDAC tumor growth by inhibiting the growth of CAFs and normalizing the immune response." (PMID 37733442, 2023). "The gene expression levels of LDHA and GLUT1 were examined in SCC25-EBV tumor cells to investigate whether the malignant phenotypes of OSCC were induced by the Warburg effect." (PMID 37762374, 2023). "Notably, LDHA, SHC1, and EPHX1 exhibited heightened expression levels in tumor tissues, while MYO6 and TLE1 displayed diminished expression compared to normal tissues." (PMID 37965333, 2023). "Inhibitors of LDHA, such as oxalate and gossypol, can cut off the ATP supply of tumor cells without affecting the direct utilization of pyruvate in normal cells." (PMID 37298317, 2023). "While the mRNA expression of LDHA was not significantly positivity correlated with stemness markers in patient GBM tumor samples, this can potentially be explained due to differences in protein abundance/activity that do not always correlate with mRNA levels." (PMID 37420311, 2023). "While the extracellular tumor-linked roles of PGAM1, LDHA, PKM, TPI1, and PGK1 have not been tested, the anti-tumor actions of ALDOA 13, 18, ENO1 16, 18, and GAPDH 20 were reported." (PMID 37056934, 2023). "In addition to LDHB, LDHA, as a component of LDH, also plays an important role in tumor proliferation." (PMID 37582735, 2023). "So KPC-ABHD17C-vector-LDHA-Ctrl, KPC-ABHD17C-vector-LDHA-KD, KPC-ABHD17C-OE-LDHA-Ctrl, KPC-ABHD17C-OE-LDHA-KD were constructed for subsequent research, and the growth of KPC-ABHD17C-OE-LDHA-KD tumor was significantly slower than that of KPC-ABHD17C-OE-LDHA-Ctrl with complete glycolysis." (PMID 37273016, 2023). "In contrast, sex, age, grade, tumor size, metastasis, and LDHA expression were not identified as independent predictors." (PMID 37547725, 2023). "Finally, it should be marked that the detailed mechanism between LDHA/LDHB and tumor immune needs further clarification." (PMID 37547725, 2023). "Considering that TGF-β is vital for the regulation of LDHA and tumor migration, we deduced that the NSG1/TGF-β axis might induce an EMT-like phenotype in ESCC cells by activating LDHA." (PMID 37872157, 2023). "Further TIMER2 and TISIDB databases analysis manifested the close relationship between LDHA/LDHB expression and immune infiltrates (including immune cells and immune inhibitors) in >500 ccRCC patients, which indicates the complex tumor microenvironment (TME) of ccRCC." (PMID 37547725, 2023). "This suggests that simultaneous inhibition of LDHA and LDHB could attenuate tumor aerobic glycolysis." (PMID 37576895, 2023). "NK cells from the mice challenged with melanoma or pancreatic cancer cells that were LDHA deficient, and therefore did not secrete high levels of lactate, had enhanced IFN-γ and Gzmb production and tumor killing." (PMID 36710923, 2023). "In silico analysis on a single‐cell RNAseq database from invasive and central GB areas demonstrated a similar pattern, with preferential expression of LDHA in the central area and LDHB in the peripheral area albeit mRNA of both enzymes was found in a portion of invasive tumor cells." (PMID 36278433, 2022).
tumor (continued). "LDHA and ENO1, two critical enzymes of glucose anaerobic oxidation, are succinylated and crotonylated by CPT1A and CBP, respectively, to upregulate the production of lactate, aggravating tumor development." (PMID 36577755, 2022). "Previous studies have confirmed that phosphofructokinase (PFK), hexokinase 2 (HK2), lactate dehydrogenase A (LDHA), and pyruvate kinase 2 (PKM2) are the key proteins in the metabolic pathway of tumor aerobic glycolysis, which are potential targets for tumor drug therapy." (PMID 36467556, 2022). "Indeed, the GPx2 KD tumor expressed notably higher levels of glucose transporter GLUT1 (SLC2A1), aldolase-A (ALDOA), phosphoglycerate kinase (PGK1), and lactate dehydrogenase A (LDHA) than in the control tumor." (PMID 35193955, 2022). "Such as methylation of the LDHA promoter, hypermethylation of the LDHB promoter leads to suppression of LDHB expression and correlates with the metastatic potential of the tumor." (PMID 36551514, 2022). "In comparison with peri-tumor tissues, most of the 24 cancer types in TCGA had overexpressed mRNA levels of LDHA, but not LDHB." (PMID 35637958, 2022). "Thus, LDHA and LDHB had a distinct spatially restricted expression pattern in the tumor core but were found both expressed in invasive cells." (PMID 36278433, 2022). "As an important regulator of Wnt transduction in the canonical signaling pathway in tumours, Dickkopf-related protein 3 (DKK3) negatively regulates aerobic glycolysis [HK2, HIF-1α, GLUT-1, LDHA and 3-phosphoinositide-dependent protein kinase-1 (PDK-1)] in BxPC-3 cells." (PMID 36578477, 2022). "Expression of MCT4 and combined LDH (LDHA and LDHB) in the tumour epithelium are important in determining clinically significant intermediate-risk disease, while MCT1 expression may also play a role in more aggressive tumours." (PMID 35075123, 2022). "Through suppressing the expression of PKM2, GLUT1 and LDHA in MCF-7 and MDA-MB-231 cells, quercetin limited the rate of glucose absorption and lactate generation, which in turn modulated the pH of the tumor microenvironment and restricted the energy flow into tumor cells." (PMID 36339566, 2022). "Finally, overexpression of TPI1 increased expression of N-cadherin, vimentin, LDHA, p-mTOR, and CDCA5, whereas reduced E-cadherin in tumor tissues as demonstrated by WB." (PMID 35509067, 2022). "An LDH inhibitor (GSK 2837808A, potently inhibiting both LDHA and LDHB) abrogated the increase in cytokine production in the presence of lactate, indicating an active lactate-to-pyruvate enzymatic conversion activity in this tumor-like metabolic environment." (PMID 35452600, 2022). "Quercetin could reduce the acidity of the tumor microenvironment by inhibiting the glycolysis-related proteins expression of PKM2, GLUT1 and LDHA in MCF-7 and MDA-MB-231 cells, thus inhibiting glucose uptake and lactate production." (PMID 36339566, 2022). "The results confirm that antagomir‐EBV‐miR‐BART18‐3p decreased EBV‐miR‐BART18‐3p expression and also demonstrate that antagomir‐EBV‐miR‐BART18‐3p decreased the levels of LDHA and FASN, as well as Ki67 (a recognized tumor malignant phenotype marker) in tumor tissues." (PMID 36307872, 2022). "Even under low O2 concentration, double LDHA/B KO cells still rely on TCA and mitochondrial respiration to support tumor growth, which could be further inhibited by irradiation." (PMID 36278433, 2022). "In high %GP4 tumours, PDHA1 was significantly lower compared to low %GP4 tumours, while LDHA/PDHA1 was significantly higher, which provides indirect evidence for a shift from oxidative to glycolytic metabolism associated with the emergence of a more glycolytic cell population." (PMID 35075123, 2022). "Moreover, the expression levels of hypoxia-inducible factor-1 alpha (HIF1A) and lactate dehydrogenase A (LDHA), were observably upregulated in tumor cells from solid LUADs." (PMID 36138435, 2022).
tumor (continued). "In addition, immunohistochemistry of the tumor sections showed that the expression levels of key glycolytic enzymes PGK1 and LDHA decreased via the treatment with berberine." (PMID 35559258, 2022). "Furthermore, the administration of SGC707, a selective inhibitor of PRMT3, disrupted the PRMT3‐mediated LDHA methylation and abolished PRMT3‐induced HCC glycolysis and tumour growth." (PMID 35090076, 2022). "In terms of cellular immunity, the deactivation of LDHA leads to decreased lactic acid production and neutralization of the tumor pH, which then mediates the aggregation of CD8+ T cells and NK cells, and suppresses tumor progression." (PMID 34307169, 2021). "Genetic disruption or silencing of LDHA and LDHB in tumor cells inhibits tumor growth." (PMID 34394085, 2021). "In addition, an observed albeit modest decrease in promoter H3K3me4 (marker of active transcription) was observed in LDHA, PDL2, and PDL1 upon induced expression of the IDH mutant, which is in line with our results from human LGG tumor samples." (PMID 33532725, 2021). "LDHB expression does not have a pattern like LDHA, it can vary depending on the tumor type and the tumor’s dependence on aerobic glycolysis." (PMID 33668689, 2021). "Another potential therapeutical approach to inhibit LDHA is FX11, which caused a reduction in the proliferation of PDA cell lines and of tumor growth in vivo without side effects." (PMID 33804240, 2021). "We also detected enhanced nuclear immunoreactivity of LDHA in GBM that was not previously reported supporting a role for nuclear LDHA in promoting more aggressive tumor phenotype." (PMID 33996536, 2021). "By inducing glycolysis-related genes products such as hexokinase 2 (HK2), lactate dehydrogenase A (LDHA), and glucose transporter 1 (GLUT1, also known as solute carrier family A1, SLC2A1), HIF-1α switches the glucose metabolism of hypoxic tumor cells to the glycolytic pathway." (PMID 35096814, 2021). "Using the integrated data of the tumor transcriptome from the TCGA database and the normal pancreas transcriptome from the Genotype-Tissue Expression (GTEx) database, we showed that LDHA, SLC2A1, and PGK1 were upregulated in tumor samples (logFC > 2, P < 0.05)." (PMID 33777046, 2021). "In the presence of tumor cells, cell and vessel densities and the percentages of cells staining positive for CAIX, LDHA and Ki67 exceeded the numbers that were detected in specimens without tumor cells (p < 0.001, p = 0.006, p = 0.003, p = 0.002, and p < 0.001, respectively)." (PMID 34439213, 2021). "Thus, the increased expression of LDHA induced by TH, together with the up-regulation of GLUT-1 and various glycolytic genes, reinforces the concept that TH is a potent tumor-promoting agent." (PMID 34205977, 2021). "The inhibition of LDHA in vivo led to reduced growth of MYC-driven tumours but not MYC-independent tumours." (PMID 34445233, 2021). "In addition to LDHA, the activity of lactate dehydrogenase B (LDHB), which also supports the conversion of lactate to pyruvate, is frequently upregulated in tumor cells and can thereby mediate therapy resistance." (PMID 34359663, 2021). "Moreover, we found that LDHA not only promoted PTC migration and invasion but also enhanced tumor growth both in vitro and in vivo." (PMID 33795650, 2021). "In this study, we observed that Fraction B not only significantly suppressed the expression of key enzymes responsible for glycolysis, LDHA, and glutamine transporter, SLC1A5, in the tumor tissues, but also reduced the metabolites of glycolysis and glutamine levels." (PMID 34349642, 2021). "The significant reduction of LDHA and SLC1A5 protein expression in Fraction B treated tumor may represent additional layer of action or regulation and deserves further investigation." (PMID 34349642, 2021). "Gene set enrichment analysis (GSEA) revealed that LDHA was significantly highly expressed in COAD compared with non-tumor tissues according to the GSE9348 and GSE23878 datasets (all p < 0.01)." (PMID 34307169, 2021).
tumor (continued). "The expression levels of PKM2 and LDHA were significantly decreased together with β-catenin and proliferating cell nuclear antigen (PCNA) by KYA1797K treatment in the tumour area of the small intestine from Apcmin/+ mice compared with those of vehicle-treated mice." (PMID 33071283, 2021). "Importantly, these results suggested that BSJPF inhibits tumor proliferation by enhancing GLUT1- and LDHA-related glycolysis." (PMID 34002799, 2021). "In tumor cells, antagomir treatment significantly reduced the miR-375 amount in both cell lines, which was in line with increased LDHB and reduced PFKFB3 mRNA expression, while LDHA remained unaltered." (PMID 34158867, 2021). "The mRNA expression of LDHA was significantly upregulated in tumor tissues compared to the adjacent nontumoral normal tissue." (PMID 34185423, 2021). "In fact, a negative correlation between tumor LDHA expression and patient survival has been found in melanoma." (PMID 34079545, 2021). "CCL5 and CCL18 up-regulate the activity of various glycolysis factors, including lactate dehydrogenase A (LDHA) and glucose-6-phosphate dehydrogenase (G6PD), which can advance glycolysis in tumor cells, lead to accumulation of lactic acid in TME and restrain the immune system’s anti-tumor reaction." (PMID 34368156, 2021). "Taken together, the tumor-suppressive activity of miR-449a in NPC cells might be attributed to the inhibition of expression of multiple cell growth regulators, such as LDHA and EZH2." (PMID 32752071, 2020). "Tumor growth was inhibited by treatment with tamoxifen plus GDC-0032, but not by tamoxifen alone, and this combined treatment resulted in decreased FOXM1 and LDHA expression." (PMID 32976773, 2020). "Although the substrate preference of LDHA and LDHB differs, these observations indicate that substrate affinity and the extent of metabolic adaptation in tumors may vary depending on both tumor-specific intrinsic and extrinsic cues." (PMID 33324565, 2020). "In addition to their widespread expression in normal tissues, LDHA and LDHB are often overexpressed in tumor tissues, including TNBC." (PMID 33324565, 2020). "Studies investigating the LDH expression levels in tumor and serum found that high tissue expression is not entirely consistent with elevated serum levels, indicating that tumor LDHA expression and serum levels are two independent predictors of the disease." (PMID 32197468, 2020). "But LDHA inhibitors had some limitations, such as high toxicity, low drug exposure or a lack of LDHA dependence in human tumor inhibitors." (PMID 32211335, 2020). "In an anoxic state, LDHA can catalyze the final reversible AEG reaction, which involves converting pyruvate in tumor cells to lactic acid, thus increasing the AEG activity of tumor cells." (PMID 32076440, 2020). "In addition, the expression levels of miR-103a-3p and the key glycolytic molecules HK2, LDHA and PFK1 in tumour tissues from miR-103a-3p antagomir group were lower than control values." (PMID 33218358, 2020). "Homogeneous cytoplasmic LDHA and granular/mitochondrial GLS stainings were observed in normal and tumour cells, and the levels of these metabolic enzymes were slightly elevated in tumour tissues." (PMID 32899149, 2020). "Furthermore, the knockout of lactate dehydrogenase A(LDHA), a key enzyme in glycolysis, resulted in the reduction in MDSCs in tumor tissues and the spleen." (PMID 33027968, 2020). "Herein, we found that LDHA expression and lactate levels in both the tumor and contralateral areas are alike; similar to the results previously reported in a patient-derived GBM tumor." (PMID 32575619, 2020). "The significant delay in tumor growth was accompanied by increased PK activity and decreased LDHA activity in plasma and tumor lysates, and reduced detection of PKM2 and expression of LDHA in tumor tissues, along with significantly decreased tumor proliferation." (PMID 31527446, 2019).
tumor (continued). "The role of LDHA and LDHB in tumor biology is more complex than was initially expected." (PMID 31035592, 2019). "Inhibition of LDHA by FX-11 can reduce the ability of cancer cells to metabolize pyruvate to lactate, halting the regeneration of NAD+, which is required for sustained glycolysis, and consequently prevent tumor cell proliferation." (PMID 31527446, 2019). "In tumour tissues from the BGC‐823‐xenografted nude mice treated with DT‐13‐TPT combination, the expressions of aerobic glycolysis‐related enzymes (HK II, PKM2, LDHA, and so on) were inhibited." (PMID 31397978, 2019). "At the same time, LDHA, ADM, SLC2A1 and CA9 were also decreased in EP300 knockdown ESCC cells, indicating that EP300 may promote tumor growth and progress via hypoxia in ESCC." (PMID 31632486, 2019). "LDHA and LDHB, two isoenzymes of LDH, participate in tumor stroma metabolic interaction and exchange of metabolic fuel and thus could serve as potential anticancer drug targets." (PMID 31146503, 2019). "However, the expression of glycolytic enzymes such as LDHA and PGK1 in the Myc signaling pathway was decreased in ACTH-PA, which was consistent with the reduced glycolysis observed in this tumor type." (PMID 30532734, 2018). "Kayser et al101 found that almost 90% of NSCLC patients were positive for LDHA, while all non‐tumor lung tissues showed negative LDHA expression." (PMID 30403008, 2018). "Previous LDHA knockdown studies that show tumour attenuation have not verified the knockdown status of other LDH family members." (PMID 29601482, 2018). "We found that oxamate significantly attenuates MB aerobic glycolysis, proliferation and motility however, unlike studies in other tumours; our LDHA knockdown studies did not result in the same functional observations." (PMID 29601482, 2018). "The transcriptional activity of c-myc and the stabilization of hypoxia inducible factor 1 alpha (HIF1α) in cancer cells enhance the expressions of most glycolytic enzyme genes, including lactate dehydrogenase-A (LDHA) and GLUT1, which in turn increase tumor aggressiveness and lead to poor survival." (PMID 30258444, 2018). "Indeed, inhibitors of glycolytic enzymes such as hexokinase 2 (HK2), phosphofructokinase 2 (PFK2), pyruvate kinase M2 (PKM2), lactate dehydrogenase A (LDHA), and pyruvate dehydrogenase kinase (PDK) show anti-tumor effects." (PMID 30602670, 2018). "The induction of LDHA was not only seen in tumor cells but also in the non-neoplastic host compartment, an observation that was possible due to the species-specific SRM workflow established in said study." (PMID 28265552, 2017). "GLUT1, HK2, and LDHA were previously found to be regulated in an oncogenic Kras dependent manner, suggesting that they may be important for KRAS-driven tumor growth." (PMID 28915575, 2017). "Similarly, deletion of LDHA in myeloid cells promoted accumulation of macrophages with a CD86high and MCP-1high M1-like phenotype that suppressed tumor growth." (PMID 29152106, 2017). "Moreover, the high conversion rate of pyruvate into lactate, via the enzymatic activity of lactate dehydrogenase A (LDHA), is usually assumed to be the major mechanism responsible for tumour acidity." (PMID 26099350, 2016). "Currently, there are, however, no suitable LDHA inhibitors available for tumor therapies in the clinic." (PMID 26269128, 2016). "Furthermore, we analyzed the mRNA expression level of LDHA in 31 NPC samples and 10 non-tumor nasopharyngeal epithelial tissues from GSE12452 database." (PMID 27458165, 2016). "To further investigate the biological significance of LDHA in tumor growth, xenograft experiments were performed, and we found that ectopic expression of LDHA in MCF-7 and MDA-MB-231 cells led to a significant increase in tumor size and weight." (PMID 26902416, 2016).